SOD2 (superoxide dismutase 2)
Diseases named in the same sentence as SOD2 in open-access papers (continued):
Sharing a sentence is not in itself a finding about the gene and the disease.
allergic disease (2 papers, 2021 to 2023). An immune response that occurs following re-exposure to an innocuous antigen, and that requires the presence of existing antibodies against that antigen. "Pathways related to intracellular signalling pathway, stress response, VEGF and MTOR related, the latter showed in the last years to be related with allergy; and oxidative phosphorylation are up-regulated, like FOXP1, SERPIN family, SOD2, caspase family, PGF, CYB5B, SERP1 and SLC25A4." (PMID 34784380, 2021).
Arterial thrombosis (2 papers, 2024 to 2025). The formation of a blood clot inside an artery. "Consequently, SOD2 deficiency heightened susceptibility to arterial thrombosis." (PMID 41300443, 2025). "Although platelet-specific deletion of SOD2 in mice does not impair primary hemostatic functions such as adhesion and aggregation, it markedly alters mitochondrial function, ROS production, calcium handling, thrombin generation, and predisposes to arterial thrombosis during aging." (PMID 41300443, 2025).
aspergillosis (2 papers, 2024). Aspergillosis is an infection, growth, or allergic response caused by the Aspergillus fungus. "Triple deletion of sod1, sod2, and sod3 genes did not decrease the virulence of A. fumigatus in an immunocompromised murine aspergillosis model; however this triple mutant exhibited increased sensitivity to killing by alveolar macrophages of immunocompetent mice." (PMID 39728319, 2024).
autoimmune glomerulonephritis (2 papers, 2024 to 2025). An autoimmune form of glomerulonephritis (disease). "There is evidence that in autoimmune glomerulonephritis, in synergy with the deposition of autoantibodies in glomeruli (the first hit of the disease), the synthesis of SOD2 is up-regulated in podocytes, which is an indirect sign of oxidative stress." (PMID 39765847, 2024). "In MN, a concept appears that a second wave of antibodies targeting superoxide dismutase 2 (SOD2) is generated in autoimmune glomerulonephritis and may negatively influence the clinical outcome." (PMID 41154542, 2025). "Here, we discuss the concept that a second wave of antibodies targeting SOD2 is generated in autoimmune glomerulonephritis and may negatively influence the clinical outcome." (PMID 39765847, 2024).
B-cell lymphoma (2 papers, 2023). "On the other hand, the manganese superoxide dismutase (SOD2 Val16Ala) polymorphism (whose functionality is yet to be described) consistently increased the risk of mature B-cell lymphoma (even across different subtypes)." (PMID 37107311, 2023). "Moreover, a statistically significant association has been identified between B-cell lymphomas and the polymorphism of manganese superoxide dismutase (SOD2 Val16Ala)." (PMID 37759977, 2023).
Balkan endemic nephropathy (2 papers, 2019 to 2023). "The results of this study have shown that individuals with both copies of variant SOD2 allele, known to be associated with lower mitochondrial antioxidant protection, are at a significantly higher risk of Balkan endemic nephropathy." (PMID 31382611, 2019). "Since these processes might be mediated by free radicals produced in the course of OTA or/and AA metabolism, it was speculated the variant SOD2 allele would be associated with a higher risk of Balkan endemic nephropathy." (PMID 31382611, 2019). "The association of GPX1 and SOD2 contributes to ochratoxin (OTA)-induced nephrotoxicity and Balkan endemic nephropathy." (PMID 37893028, 2023). "Indeed, our data demonstrated that carriers of one copy of variant SOD2 allele in areas of Balkan endemic nephropathy had higher risk of BEN, when compared to individuals with both wild type SOD2 gene variants, although the difference observed was not statistically significant." (PMID 31382611, 2019).
bladder transitional cell carcinoma (2 papers, 2023 to 2025). The most common morphologic subtype of urinary bladder carcinoma (over 90% of cases). "This study aimed to investigate the association of GPX1 (rs1050450) and SOD2 (rs4880) genetic variants with the urothelial bladder cancer (UBC) risk independently and in combination with smoking." (PMID 36676755, 2023).
Chagas disease (2 papers, 2018 to 2023). A parasitic infection caused by Trypanosoma cruzi. "In this study, we have investigated the effects of manganese superoxide dismutase (SOD2 or MnSOD) deficiency on mitochondrial function and oxidative stress during Chagas disease." (PMID 30044789, 2018). "We surmise that SIRT/PARP1 balance along with activators of SOD2 will provide promising new therapeutic strategies for arresting chronic oxidative and inflammatory stress and cardiac dysfunction in Chagas disease." (PMID 30044789, 2018).
chronic granulomatous disease (2 papers, 2017 to 2021). Chronic granulomatous disease (CGD) is a rare primary immunodeficiency, mainly affecting phagocytes, which is characterized by an increased susceptibility to severe and recurrent bacterial and fungal infections, along with the development of granulomas. "On a preclinical level, anakinra upregulates SOD2 in murine models of chronic granulomatous disease (CGD) and cystic fibrosis." (PMID 34207085, 2021). "Relative basal expression of SOD2 and TXN in chronic granulomatous disease (CGD) monocytes compared to monocytes from healthy individuals." (PMID 29375548, 2017).
cognition (2 papers, 2022 to 2024). Intellectual or mental process whereby an organism becomes aware of or obtains knowledge. "TLB:Improves cognitive deficits in both animal models.Ameliorates neuroinflammation and oxidative stress by inhibiting the HMGB1/TLR4/NF-κB signaling pathway and activating the SIRT3/SOD2 pathway, which helps to restore redox homeostasis and suppress neuroinflammation." (PMID 39459209, 2024).
colorectal tumor (2 papers, 2018 to 2019). "The expression of SOD2 is increased in pre-malignant (T and N) stages during colorectal carcinogenesis whereas SOD1 is expressed only in colorectal tumors." (PMID 31623294, 2019).
cryptococcosis (2 papers, 2014 to 2021). An acute or chronic, localized or disseminated infection by Cryptococcus neoformans. "Further, decoupling Cuf1 regulation of Sod2 localization compromises the ability of C. neoformans to colonize organs in murine models of cryptococcosis." (PMID 33567338, 2021). "Indeed, the sod2 mutant showed increased sensitivity to oxidative stress, reduced growth at the host body temperature of 37°C compared to the wild type, and avirulence in a murine inhalation model of cryptococcosis." (PMID 24586538, 2014).
dental caries (2 papers, 2018 to 2024). The decay of a tooth, in which it becomes softened, discolored, and/or porous. "Polymorphisms in SOD2 and SOD3 are potentially valuable biomarkers of OHRQoL in Para athletes with dental caries experience." (PMID 39109770, 2024). "This study provides new evidence on the impact of genetic polymorphisms in SOD2 and SOD3 genes on the OHRQoL of Para athletes with dental caries experience." (PMID 39109770, 2024). "Polymorphisms of the SOD2 and SOD3 genes may be important biomarkers of OHRQoL in Para athletes with dental caries experience." (PMID 39109770, 2024). "The aim of this study was to evaluate whether polymorphisms in SOD2 and SOD3 genes modulate the oral health-related quality of life (OHRQoL) of Para athletes with dental caries experience." (PMID 39109770, 2024). "The positive hypothesis is that polymorphisms of SOD2 and SOD3 genes modulate the impact of OHRQoL in Para athletes with dental caries experience." (PMID 39109770, 2024). "Thus, this study aimed to evaluate whether polymorphisms of SOD2 and SOD3 genes are associated with OHRQoL in Para athletes with dental caries experience." (PMID 39109770, 2024).
disc degeneration (2 papers, 2019 to 2025). "SOD2 has been recently demonstrated to be an important effector of FOXO signaling in disc degeneration, and its reduction is correlated with decrease in the expression of FOXO transcription factors." (PMID 31569377, 2019). "Our investigations found that the expression levels of SOD2 and CAT were significantly reduced in disc degeneration, which may contribute to NPC dysfunction and disc degeneration." (PMID 41614764, 2025).
endometrioid ovarian carcinoma (2 papers, 2022 to 2024). "Further study confirmed that SOD2 overexpression is a biomarker in predicting poorer prognosis with endometrioid ovarian carcinoma and shows extreme resistance to chemotherapeutics-mediated oxidative stress." (PMID 36233276, 2022).
Fabry disease (2 papers, 2022 to 2025). Fabry disease (FD) is a progressive, inherited, multisystemic lysosomal storage disease characterized by specific neurological, cutaneous, renal, cardiovascular, cochleo-vestibular and cerebrovascular manifestations. "Elsaid cleverly utilized a zebrafish model that does not produce GB3 to investigate other potential therapeutic targets for Fabry disease, particularly the implications of the Sod2(superoxide dismutase 2) activity mechanism." (PMID 40075521, 2025). "The mRNA expression of the angiogenic factors, eNOS, and ANG2, and superoxide dismutase 2 (SOD2), mitochondrial antioxidant, were significantly decreased in GLA‐mutant kidney organoids, which is compatible with the phenotypes of vasculopathy in Fabry disease." (PMID 35322595, 2022).
follicular thyroid cancer (2 papers, 2022 to 2024). "In contrast, in mice with aggressive follicular thyroid cancer, the overexpression of SOD2 reduced tumor proliferation and improved mortality rates." (PMID 36552527, 2022). "These authors observed a reduction in Sod2-to-Gpx1 and Sod2-to-catalase ratios in DRP-TpoKO mice (follicular thyroid cancer model), indicating an inability to scavenge ROS." (PMID 39125641, 2024).
fungal infection (2 papers, 2022). "A study suggested that TLR4 is an upregulated representative target in keratitis of bacterial infection, whereas SOD2 is an upregulated representative target in keratitis of fungal infection from Differentially Expressed Genes (DEGs)." (PMID 35216171, 2022).
fungal keratitis (2 papers, 2017 to 2021). "The average ratios of the expression levels of the Hmox1, Nos3, Hif1a, Sod2, Sod3, and Gpx2 genes increased more than 2-fold (p < 0.05) at day 1 p.i. in the fungal keratitis model, whereas the expression ratios of the Hif1an and Prdx6 genes decreased more than 2-fold (p < 0.05)." (PMID 28874754, 2017).
HCMV infection (2 papers, 2022 to 2024). "Moreover, RNA2.7 can protect CD14+ monocytes against reactive oxygen species (ROS)-induced apoptosis via increasing superoxide dismutase 2 (SOD2) and supporting latent HCMV infection." (PMID 39724092, 2024). "Interestingly, SOD2 mRNA was found to be upregulated in a previous unbiased screen for altered transcripts after HCMV infection of monocytes." (PMID 35215840, 2022).
Hepatitis B (2 papers, 2019 to 2024). "The inhibition of hepatitis B replication exerted by the triterpene is based on the downregulation of mitochondrial superoxide dismutase (SOD2) through the dephosphorylation (Ser133) of the cAMP response element-binding transcription factor at its binding site with the SOD2 promoter." (PMID 31574991, 2019). "Desmoplakin (DSP, P15924) is a relevant drug target for the treatment of pneumonia, while SOD2 is used in the treatment of Hepatitis B. Currently, no drug targets have been found for the treatment of kidney and thyroid-related diseases." (PMID 39192889, 2024).
Hypercholesterolemia (2 papers, 2011 to 2022). An increased concentration of cholesterol in the blood. "Decreased SOD2 activity increased measures of cellular and mitochondrial oxidant stress and, moreover, atherosclerotic lesion development under conditions of hypercholesterolemia and ETS exposure." (PMID 21169125, 2011).
inflammatory bowel disease (2 papers, 2022 to 2025). A spectrum of small and large bowel inflammatory diseases of unknown etiology. "Overproduction of reactive oxygen species and antioxidant superoxide dismutases (SOD1, SOD2) dysregulation contribute to chronic inflammation such as generated in inflammatory bowel diseases (IBD)." (PMID 40000394, 2025).
knee osteoarthritis (2 papers, 2023 to 2024). "In knee osteoarthritis, SIRT3 regulates Atrogin-1 and MuRF-1 levels by decreasing SOD2 acetylation and reducing reactive oxygen species (ROS) levels." (PMID 39519152, 2024).
laryngeal carcinoma (2 papers, 2021 to 2023). Carcinoma that arises from the laryngeal epithelium. "The influence of serum zinc levels on survival in laryngeal cancer patients can be multiplied if correlated with adequate antioxidant enzymes polymorphisms: SOD2 TC/TT and CAT CC." (PMID 34200699, 2021). "The goal of the current study was to evaluate whether circulating zinc levels, at the time of diagnosis, and polymorphisms in SOD2, CAT and GPX1 are associated with survival among laryngeal cancer patients." (PMID 34200699, 2021).
lupus nephritis (2 papers, 2023 to 2024). Glomerulonephritis in the context of systemic lupus erythematosus. "Similar findings have been reported in subjects affected by Lupus nephritis, where high levels of circulating anti-SOD2 IgG2 were found during the flare of the disease and, according to proteinuria then decreased after effective treatment." (PMID 37176025, 2023). "High levels of circulating anti-SOD2 antibodies have been reported in either MN and Lupus nephritis, two common forms of autoimmune Gn." (PMID 37176025, 2023).
myelofibrosis (2 papers, 2018 to 2021). A partial or complete replacement of the bone marrow stroma by fibrous tissue. "In line with this, a decrease in SOD2 and further ROS accumulation was reported after overexpression of miR-382-5p in primary myelofibrosis CD34+ cells, linked to deregulation of the TGF-β1/miR-382-5p/SOD2 pathway." (PMID 34199590, 2021).
pancreatitis (2 papers, 2007 to 2020). Inflammation of the pancreas. "As expected, PGC-1α deficiency triggered the down-regulation of Sod2 and Prdx3 under basal conditions and during pancreatitis." (PMID 32961723, 2020).
papilloma (2 papers, 2011 to 2017). A benign epithelial neoplasm that projects above the surrounding epithelial surface and consists of villous or arborescent outgrowths of fibrovascular stroma. "Western blot analysis also showed similar observations of GPx and SOD2 protein in both preneoplasia and papilloma." (PMID 28441719, 2017). "Moreover, BRB increased the mRNA expression of GPx 1, 2, 3, 4, and SOD2 in papilloma." (PMID 28441719, 2017).
parasitemia (2 papers, 2018 to 2022). "E8.5 infected mice had elevated transcripts for Ifnγ, Tnf, Il10, Cox1, Cox2, Sod1, Sod2, Cat, and Nrf2, while Sod3 was the only transcript that correlated with parasitemia." (PMID 35312688, 2022).
polycystic ovaries (2 papers, 2018 to 2023). "Compared with normal ovaries, the expression of SOD2 was stronger in the homogenates of polycystic ovaries with cancer at the early stage (PCOC-ES) and the late stage (PCOC-LS)." (PMID 30596106, 2018). "Increased expression of SOD2 in ovarian cysts and tumors in PCOC hens observed in this study may be a response to the oxidative stress due to an increased infiltration of immune cells (macrophages and IL-16-expressing cells) in polycystic ovaries and the subsequent development of PCOC." (PMID 30596106, 2018).
sarcoidosis (2 papers, 2016 to 2021). Sarcoidosis is a multisystemic disorder of unknown cause characterized by the formation of immune granulomas in involved organs. "Several proteins were identified with higher abundance in BAL of sarcoidosis patients, including cadherin 5 (CDH5), transferrin (TF), C-C motif chemokine 24 (CCL24), interleukin 15 (IL15) apolipoprotein A (LPA) and mitochondrial superoxide dismutase (SOD2)." (PMID 27259755, 2016).
selenium deficiency (2 papers, 2021 to 2025). A nutritional deficiency disease resulting from inadequate selenium levels in the body, which can lead to impaired function of selenoproteins essential for antioxidant defense and thyroid hormone metabolism. "Sod1 and Sod2 mRNA were unaffected by maternal selenium deficiency." (PMID 33769708, 2021). "Next, we examined if non‐seleno‐dependent antioxidants were dysregulated in the kidneys of offspring exposed to maternal selenium deficiency and demonstrated no changes in Sod1 or Sod2 mRNA." (PMID 33769708, 2021).
sickle cell anemia (2 papers, 2021 to 2023). "For example, the common polymorphism in SOD2 (SOD2V16A) in patients with sickle cell disease associates with increased cardiovascular consequences by curtailing mitochondrial complex IV activity and increasing ROS production." (PMID 36763969, 2023).
skin atrophy (2 papers, 2012 to 2015). The degeneration and thinning of the epidermis and dermis. "Deletion of Sod2 in fibroblasts of the connective tissue-rich skin resulted in skin atrophy, a key feature of ageing, with reduced thickness of all the skin layers (Fig8A and B)." (PMID 25520316, 2015).
Stillbirth (2 papers, 2022 to 2024). Death of the fetus in utero after at least 22 weeks of gestation. "On the other hand, SOD2, a key molecule involved in the cytokine pathway, was the only gene found to be upregulated in the different conditions studied (spontaneous preterm birth, stillbirth, and foetal facet from spontaneous miscarriage)." (PMID 38791219, 2024). "In our earlier study, we discovered that SOD2, the mitochondrial superoxide dismutase isoform, was upregulated, being expressed in both fetal and maternal tissues in sporadic miscarriage, in addition to in stillbirth and in spontaneous preterm birth." (PMID 36209198, 2022).
subarachnoid haemorrhage (2 papers, 2022 to 2023). "SIRT3 plays an essential neuroprotective role in subarachnoid haemorrhage; however, changes in SOD2, an important downstream molecule of SIRT3, tend to vary according to the current research." (PMID 37009480, 2023). "There is evidence that the expression of SOD2 increases after subarachnoid haemorrhage and climbs to the top at 24 h because of neuroinflammation and neuronal apoptosis." (PMID 37009480, 2023). "However, subsequent research revealed that the levels of both SIRT3 and SOD2 decreased following subarachnoid haemorrhage." (PMID 37009480, 2023).
transient cerebral ischemia (2 papers, 2016 to 2020). "In gerbil hippocampus, after transient cerebral ischemia, LA treatment attenuated superoxide anion generation and lipid peroxidation by increasing the expression of SOD1 and SOD2." (PMID 32629814, 2020).
transitional cell carcinoma (2 papers, 2018 to 2019). A malignant neoplasm arising from the transitional epithelium, usually affecting the urinary bladder, ureter, or renal pelvis. "Regarding the influence of polymorphisms in genes encoding antioxidant enzymes and risk of transitional cell carcinoma, we showed that the presence of variant SOD2 allele modifies the cancer risk in BEN patients by a 1.5-fold increase." (PMID 31382611, 2019).
tuberculosis (2 papers, 2014 to 2023). A chronic, recurrent infection caused by the bacterium Mycobacterium tuberculosis. "SOD2 activity was regulated at the transcriptional, posttranscriptional, and posttranslational level, which makes SOD2 a promising new target for tuberculosis treatment." (PMID 36819778, 2023).
uremia (2 papers, 2016 to 2025). A clinical syndrome associated with the retention of renal waste products or uremic toxins in the blood. "Since advanced uremia is a state of 1,25-dihydroxyvitamin D deficiency but also of vitamin D receptor deficiency and dysfunction, vitamin D receptor-related uremic effects could be involved in the J-shape of SOD2 protein that we observed." (PMID 27630759, 2016). "Among them, HMOX1, SOD2, and NOS2 have become the key targets - which is consistent with their previous research that can protect renal tubules from oxidative damage, maintain mitochondrial antioxidant capacity, and regulate the oxidative-reductive imbalance associated with uremia." (PMID 41560720, 2025).